NLRP3 (NLR family pyrin domain containing 3)
Diseases named in the same sentence as NLRP3 in open-access papers (continued):
Sharing a sentence is not in itself a finding about the gene and the disease.
breast cancer (continued). "In a recent study, it was found that fibroblasts sense DAMPs and, in response, activates the NLRP3 pathway, resulting in a pro-inflammatory signaling and secretion of IL-1β in mouse and human breast carcinomas." (PMID 33840390, 2021). "NLRP3 inflammasome inactivation, driven by miR-223-3p, increases proliferation, promotes invasion and inhibits apoptosis in breast cancer cells." (PMID 33613533, 2020). "A causal mechanism by which obesity promotes the progression of breast cancer via the NLRP3 inflammasome activation has been recently described." (PMID 33613533, 2020). "The NLRP3 inflammasome is the most extensively studied inflammasome, and activation contributes to immune system dysfunction and breast cancer metastasis by mediating the secretion of IL-1β." (PMID 32397236, 2020). "Administration of the NLRP3 selective inhibitor (OLT1177) increased responsiveness to ipilimumab in breast cancer cells and reduced cytotoxicity in AC16 cells." (PMID 33096896, 2020). "Breast cancer cells and cardiomyocytes under high glucose and exposed to ipilimumab showed a considerably higher amount of NLRP3 (green signals) than the control." (PMID 33096896, 2020). "The role of NLRP3 in tumor-associated neo-vasculature and angiogenesis has been found to regulate angiogenesis in CRC, breast cancer, NSCLC." (PMID 33613533, 2020). "Further investigations have led to the conclusion that NLRP3-mediated inflammation is responsible for tissue damage in the case of breast cancer." (PMID 33015196, 2020). "Inactivation of NLRP3 inflammasome driven by miR-233-3p has been found to decrease the expression of NLRP3 inflammasome-associated proteins, ASC, IL-1β, and IL-18 in breast cancers and suppress tumor growth." (PMID 33613533, 2020). "This pathway plays a major role in tumor lymphangiogenesis, murine lymph node, and lung metastasis, while NLRP3 expression is correlated with human mammary carcinoma development." (PMID 32635472, 2020). "NLRP3 expression in TAMs is correlated with lymph node invasion, metastasis, and survival in mammary carcinoma patients." (PMID 32635472, 2020). "NLRP3 expression in tumor-infiltrating macrophages is correlated with survival, lymph node invasion, and metastasis of mammary carcinoma patients." (PMID 33613533, 2020). "In this review, we discuss the structure, biology and mechanisms of inflammasomes with a special focus on the specific role of NLRP3 in breast cancer (BC) and in the sub-group of triple negative BC." (PMID 33014808, 2020). "We showed that activation of the NLRP3 inflammasome pathway in CAFs, a physiological sensing mechanism of tissue damage, is hijacked in breast cancer to facilitate tumour progression and metastasis." (PMID 31558756, 2019). "We found that the NLRP3 inflammasome pathway is upregulated in CAFs during spontaneous murine mammary carcinogenesis, as well as in CAFs in human breast cancer." (PMID 31558756, 2019). "Previous studies also demonstrated that NLRP3 inflammasome, and its complex (IL-11β and IL-18) promote tumor growth, proliferation, invasion and metastasis in lung cancer, melanoma, breast cancer and HNSCC." (PMID 31312615, 2019). "Validation of the transcriptome profiling results by qRT-PCR in mammary CAFs isolated from mammary tumours or from normal mammary glands by FACS confirmed the upregulation of genes related to the NLRP3 inflammasome pathway." (PMID 31558756, 2019). "It was reported that inactivation of the NLRP3 inflammasome repressed tumor growth and immunosuppression in breast cancer." (PMID 31492049, 2019). "For instance, the NLRP3 inflammasome was involved in leptin-induced growth of breast cancer cells via promotion of cell cycle progression and suppression of cell apoptosis." (PMID 31492049, 2019). "Further analysis of the CD11b+Gr1+-infiltrating cells demonstrated that depletion of NLRP3 in CAFs-attenuated recruitment of the monocytic fraction of CD11b+Gr1+ cells (CD11b+Ly6ChighLy6G−) into mammary tumours." (PMID 31558756, 2019).
breast cancer (continued). "Our results are consistent with decreased expression of the NOD-like signaling receptor, NLRP3, in all subtypes of breast cancer relative to normal controls in the TCGA datasets." (PMID 29458327, 2018). "In contrast, NLRP3 had a positive correlation with overall survival in breast cancer patients (right two panels)." (PMID 27708283, 2016). "Collectively, those results suggest that the activation of NLRP3 inflammasome promotes tumor growth and metastases in breast cancer orthotopic models." (PMID 27786298, 2016). "NLRP3 inflammasome is a main player in enhancing breast cancer cell metastasis and invasion." (PMID 39941895, 2025). "The evidence of ALKBH7 and NLRP3 co-expression proposes a novel functional link between these molecules, potentially representing a dual-function mechanism that integrates metabolic adaptation and immune signaling in breast cancer." (PMID 41373809, 2025). "Numerous studies have reported the capacity of anti-tumor drugs to stimulate the caspase-1-dependent cell death of tumor cells; however, the role of the NLRP3 inflammasome and pyroptosis in the breast cancer context is still ambiguous and requires in-depth molecular studies for a full understanding." (PMID 39940603, 2025). "For example, miR- 223 - 3p targets NLRP3 to regulate cartilage degeneration; in breast cancer, miR- 223 - 3p induces NLRP3 inflammasome inactivation, inhibits tumor growth, and enhances antitumor immunity; miR- 223 - 3p also regulates NLRP3 expression in immune cells." (PMID 40360974, 2025). "Furthermore, in vivo studies demonstrate that miR-223 overexpression significantly decreases NLRP3 inflammasome expression, leading to reduced breast cancer growth." (PMID 39125761, 2024). "NLRP3 represents a potential novel target for breast cancer treatment." (PMID 39125761, 2024). "Studies have demonstrated that miR-223 transcriptional suppression of NLRP3 could promote apoptosis in breast cancer, hepatocellular cancer, cervical cancer, and glioblastoma cells." (PMID 38543085, 2024). "In addition, recent evidence has highlighted the importance of chronic inflammation in breast cancer pathobiology, such as NLRP3 inflammasome and cytokine oncostatin M, which are involved in breast cancer signaling and reprogramming the tumor microenvironment." (PMID 38904041, 2024). "However, the precise mechanisms involved in NLRP3 inflammasome activation and its specific impact on the pathophysiology of breast cancer development need further investigations to demonstrate its potential use as a therapeutic target." (PMID 39769450, 2024). "However, given the limited evidence on NLRP3 inflammasome activation in breast cancer, further studies are needed to fully elucidate its role and potential as a therapeutic target in this context." (PMID 39336082, 2024). "Moreover, blocking P2X7 has demonstrated inhibition of breast cancer growth in mice through the NLRP3/caspase-1 pathway." (PMID 39769450, 2024). "MiR-223 may influence tumor growth and immunosuppression in breast cancer by inhibiting the NLRP3 inflammasome." (PMID 39125761, 2024). "Thus, previous studies have suggested that the NLRP3 inflammasome exerts a significant influence on breast cancer progression, metastasis, and immune response." (PMID 39769450, 2024). "While studies have suggested the pivotal function of NLRP3 and IL-1β in breast cancer development, we next investigated whether Sch B can inhibit the activation of NLRP3 inflammasome in TNBC cells." (PMID 38254674, 2024). "Furthermore, knocking out the NLRP3 inflammasome increases the apoptotic rate of MCF-7 breast cancer cells." (PMID 38001342, 2024). "In our breast cancer model, factors like immune cell infiltration and cytokine milieu may inhibit the pro-tumorigenic effects of NLRP3 inflammasome activation." (PMID 39336082, 2024). "Additionally, inhibiting the NLRP3 inflammasome has been shown to suppress breast cancer cell growth and enhance anticancer immunity." (PMID 39769450, 2024).
breast cancer (continued). "The expression level of NLRP3 in the serum of dogs with canine mammary carcinomas is significantly higher than that of dogs with benign tumours and healthy controls (p < 0.001), and the differences between the benign mammary tumour and the healthy control groups are not significant (p > 0.05)." (PMID 38731276, 2024). "Breast cancer may be treated with new ideas by targeting the NLRP3 inflammasome through gene editing." (PMID 37300757, 2023). "This review focuses on the structure, biological characteristics and mechanism of inflammasome, the relationship between NLRP3 in breast cancer Non-Coding RNAs, MicroRNAs and breast cancer microenvironment, especially the role of NLRP3 in triple-negative breast cancer (TNBC)." (PMID 37300757, 2023). "The current evidence suggests that the activation of the NLRP3 inflammasome pathway may be pros and cons in the development of breast cancer." (PMID 38031068, 2023). "Furthermore, globular adiponectin causes the integral suppression of endoplasmic stress and the NLRP3 inflammasome in restrained breast cancer cells." (PMID 36677797, 2023). "For cancer cell-derived inflammasomes, NLRP3 inflammasomes and downstream IL-1β secretion can be activated by breast cancer susceptibility gene 1 (BRCA1) deficiency through ROS production leading to promoted metastasis in breast cancer cells." (PMID 36932407, 2023). "The NLRP3 inflammasome-dependent release of IL-1β induces the expression and release of immune cells, CD4 + T cells, and IL-22, which has been linked to the initiation and progression of many types of cancer, including breast cancer." (PMID 37715239, 2023). "In addition, an increased level of NLRP3 has also been affirmed in several breast cancer cell lines in vitro and promotes tumor growth." (PMID 38031068, 2023). "However, some studies have also reported that the NLRP3 inflammasome can suppress breast cancer by inducing pyroptosis, a form of inflammatory cell death, or by activating anti-tumor immune responses." (PMID 37715239, 2023). "While the clinical evidence of the relationship between NLRP3 inflammasome activation and long-term survival is still limited, the possible roles of parenchymal or immune-stromal cells of breast cancer tissues in contributing to such carcinogenesis and progression still need to be clarified." (PMID 38031068, 2023). "Very recently, a study began to evaluate the NLRP3 expression in breast cancer patients and found that higher expression of NLRP3 may predict a poor survival." (PMID 38031068, 2023). "The activation of NLRP3 inflammasome pathways in immune-stromal and tumor parenchymal cells in the innate immune system was not isotropic and the main functions are somewhat different in breast cancer patients." (PMID 38031068, 2023). "Interestingly, NLRP3 expression is down-regulated in non-small cell lung cancers and breast cancers, and its expression positively correlates with patient overall survival." (PMID 36746533, 2023). "There are few reports on the expression and role of the NLRP3 inflammasome in breast cancer." (PMID 37300757, 2023). "NOD-like receptor protein 3 (NLRP3) may contribute to the growth and propagation of breast cancer (BC)." (PMID 36902278, 2023). "Furthermore, this study suggests NLRP3 as a valid target to increase efficacy of immunotherapy with checkpoint inhibitor in metastatic breast cancers." (PMID 35631400, 2022). "Thus, existing pre-clinical and clinical data suggest a prominent role for NLRP3 blockade in metastatic breast cancers, underscoring OLT1177 in combination with anti-PD-1 as a valid treatment option." (PMID 35631400, 2022). "From that, one hypothesis is that the inhibition of the NLRP3 may impede breast cancer tumorigenesis." (PMID 36119049, 2022). "Thus, these recent data suggest a tumor-promoting effect of NLRP3; however, its activation and role in breast cancer remain poorly defined." (PMID 35631400, 2022).
breast cancer (continued). "Moreover, CAFs can activate the NLRP3 inflammasome through sensing DAMPs in breast cancer, which leads to a pro-inflammatory signaling." (PMID 36703971, 2022). "Inflammation could be mediated by Nod-like receptor protein 3 (NLRP3) inflammasome, which was shown to promote proliferation, survival, metastasis, angiogenesis, and immunosuppression of breast cancer cells." (PMID 36517518, 2022). "Overall, these data indicate a tumor-promoting role for host-NLRP3 in breast cancer." (PMID 35631400, 2022). "Likewise, the upregulation of NLRP3 expression in breast cancer heralds a poorer five-year survival rate." (PMID 35804922, 2022). "For instance, in breast cancer, NLRP3 inflammasome-induced IL-1β production promotes infiltration with immunosuppressive myeloid-derived suppressor cells (MDSCs) and tumor-associated macrophages (TAMs), generating a TME favoring breast cancer progression and metastasis." (PMID 35740272, 2022). "In breast cancer, the NLRP3 inflammasome and IL‐1β production induce the infiltration of myeloid cells, such as tumor‐associated macrophages (TAMs) and myeloid‐derived suppressor cells, forming an inflammatory microenvironment and thus promoting breast cancer progression." (PMID 36176733, 2022). "In this context, several data suggested a role of NLRP3 activation in breast cancer development." (PMID 33840390, 2021). "Additionally, trametinib (a MEK1 inhibitor) was capable of inhibiting NLRP3 inflammasome activation and reducing breast cancer metastasis to bones." (PMID 33840390, 2021). "Additional reports have described roles for microRNA-22 (miR-22), miR-135a, and miR-233 in negatively regulating NLRP3 expression while suppressing the progression of an oral squamous cell carcinoma model, a pancreatic cancer model, and a breast cancer model, respectively." (PMID 34638239, 2021). "A recent preclinical study has clearly shown that inhibition of NLRP3 by miRNA is able to block tumor growth and the immune-resistance of breast cancer through ASC/IL-1/IL-18 pathways; this inhibition provides new clinical insights for the therapy of breast cancer." (PMID 34178667, 2021). "Similarly, NLRP3 had a positive correlation with survival in all molecular subtypes from the TCGA breast cancer dataset." (PMID 33840390, 2021). "NLRP3 inflammasome-dependent release of IL-1β induces immune cells, CD4+ T cells, and IL-22 expression and release, which has been associated to initiation and growth of many types of malignancies including breast cancer." (PMID 33840390, 2021). "Thus, RES can inhibit the NLRP3 inflammasome activation, which makes it potential application for decreasing cardiac injury in breast cancer patients and in management of patients with SARS-CoV-2 infection." (PMID 34123595, 2021). "Similarly, adiponectin prevents the development of breast cancer by inhibiting the NLRP3 inflammasome and ERS activation via the SESN2/AMPK axis." (PMID 34741186, 2021). "Moreover, activation of NLRP3 inflammasomes promoted tumor metastasis of patients with mammary carcinoma." (PMID 33821998, 2021). "Where many uncertainties are regulated and compelled to arrive at one sole cell fate, inhibiting NLRP3 activation with S. muticum extracts has been found to decrease angiogenesis, reduce cancer cell proliferation, and increase apoptosis in human breast cancer cells." (PMID 33613533, 2020). "In a recent preclinical study, the pharmacological inhibition of NLRP3 through miRNA reduced the tumor growth and the immune-resistance in breast cancer-bearing mice through ASC/IL-1/IL-18 pathways; these data provide new clinical insights for breast cancer management." (PMID 33096896, 2020). "Their findings could represent a therapeutic objective for breast cancer treatment as the miR-233/NLRP3-mediated cancer pathway is optimal for immunosuppression of breast cancer tumor cells." (PMID 33015196, 2020).
breast cancer (continued). "Notably, high glucose breast cancer cells and cardiomyocytes exposed to ipilimumab increased NLRP3 inflammasome expression." (PMID 33096896, 2020). "Our data suggest that NLRP3 activation through LPS/Nigericin treatment leads to a high level of IL-1β and IL-18 secretion in prostate cancer and glioblastoma cell lines compared to cell lines derived from lung cancer, breast cancer, and neuroblastoma." (PMID 33613529, 2020). "NLRP3 plays a key role in the pathogenesis of breast cancer and heart failure." (PMID 33096896, 2020). "In breast cancer, NLRP3 inflammasome, and IL-1β production promote the infiltration of myeloid cells such as myeloid-derived suppressor cells (MDSCs) and tumor-associated macrophages (TAMs), providing an inflammatory microenvironment thus promoting breast cancer progression." (PMID 32733479, 2020). "NLRP3 inflammasomes mediate both suppressions of apoptosis and progression of the cell cycle by leptin-dependent ROS production in breast cancer, which is mediated via estrogen receptor alpha (ERα)/reduced nicotinamide adenine dinucleotide phosphate (NADPH) oxidase signaling." (PMID 33613533, 2020). "Besides, the NLRP3 inflammasome seems to be an effector for promoting metastasis via the lymphatic system and favoring mammary carcinoma development." (PMID 32733479, 2020). "Our data suggest that targeting CAF-derived NLRP3/IL-1β pathway may be a beneficial therapeutic approach for breast cancer treatment." (PMID 31558756, 2019). "To investigate whether CAF-derived NLRP3 inflammasome is functional in other breast carcinoma models, we performed orthotopic co-injections with 4T1 cells, a highly metastatic breast cancer cell line, which models human triple negative breast cancer." (PMID 31558756, 2019). "Thus, our findings uncovered a role for CAFs in breast cancer that links tissue damage with tumour-promoting inflammation via the NLRP3 inflammasome." (PMID 31558756, 2019). "Moreover, intracellular flow cytometry analysis validated the upregulation of NLRP3 in CAFs isolated from mammary tumours." (PMID 31558756, 2019). "To assess if upregulation of the NLRP3 pathway in the stroma of breast tumours is relevant to human breast cancer, we analysed a publicly available data set of tumour stroma samples that were obtained by laser micro-dissection of breast tumours from 53 patients." (PMID 31558756, 2019). "Activation of the NLRP3 inflammasome promoted the metastasis of breast cancer cells." (PMID 31492049, 2019). "Notably, genetic ablation of CAF-derived NLRP3 or IL-1β in different syngeneic mouse models delayed mammary tumour growth and/or attenuated lung metastasis." (PMID 31558756, 2019). "CARD8, located at 19q13, encodes the caspase recruitment domain protein 8 (CARD8), also known as TUCAN, which has been reported to interact with NLRP3, suppress NF-κB activating signals and be overexpressed in human cancer tissues including ovarian, lung and breast cancer tissues." (PMID 24901306, 2014). "While GSK461364 exhibits established antitumor activity across multiple malignancies (e.g., lung carcinoma, breast cancer, hepatocellular carcinoma, osteosarcoma, and glioblastoma) and has completed phase I evaluation, our study reveals its novel anti‐inflammatory properties via NLRP3 suppression." (PMID 40948397, 2025). "Thus, it can be inferred that the activation of NLRP3 and caspase-1 in tumor parenchymal cells are mainly involved in pyroptosis and inhibit tumor growth of breast cancer, while the activation in tumor immune-stromal cells mainly contributes to inflammatory reaction and promote tumor progression." (PMID 38031068, 2023). "Among them, NLRP3 inflammasomes could mediate infiltration of CD11b+Gr1+ immune cells into mammary tumor tissues, and IL-1β could promote mammary tumor progression and tumor cell metastasis to the lung by upregulating adhesion molecules expression in primary tumors and metastatic sites." (PMID 37020871, 2023).